P2RY12 (purinergic receptor P2Y12)
Description:
Receptor for ADP and ATP coupled to G proteins that inhibit the adenylyl cyclase second messenger system. Not activated by UDP and UTP. Required for normal platelet aggregation and blood coagulation.
Synonyms: P2Y12; ADPG-R; P2Y(ADP); HORK3; SP1999; BDPLT8; P2T(AC); P2Y(12)R; P2Y(AC); P2Y(cyc)
Tractability: Small molecule: an approved drug acts on it; a structure with a bound ligand is known; a high-quality ligand is known; it belongs to a druggable protein family. Antibody: UniProt places it where antibodies can reach, with high confidence; its Gene Ontology location is reachable by antibodies, with high confidence; UniProt predicts a signal peptide or a membrane-spanning region. PROTAC: a small molecule that binds it is known.
Target class: Purine receptor; Small molecule receptor (family A GPCR); Membrane receptor; Family A G protein-coupled receptor; Nucleotide-like receptor (family A GPCR)
Chemical probes: CHEMBL2172272
Safety:
Unwanted effects reported when the protein is acted on. In parentheses: how it was acted on, where the effect was seen, and who reports it.
neurological events (source: ClinPGx)
Gene: Protein-coding gene on chromosome 3 (151,336,843 to 151,384,753, reverse strand). Ensembl gene ENSG00000169313.
Subcellular location: Cell membrane
Pathways (Reactome):
Signal Transduction: G alpha (i) signalling events; P2Y receptors
Hemostasis: ADP signalling through P2Y purinoceptor 12
Gene Ontology:
Molecular function: G protein-coupled ADP receptor activity; G protein-coupled purinergic nucleotide receptor activity; guanyl-nucleotide exchange factor activity; G protein-coupled adenosine receptor activity; G protein-coupled receptor activity
Biological process: adenylate cyclase-inhibiting G protein-coupled receptor signaling pathway; G protein-coupled receptor signaling pathway; platelet aggregation; calcium-mediated signaling; cell projection organization; cellular response to ATP; cerebral cortex radial glia-guided migration; hemostasis; lamellipodium assembly; phospholipase C-activating G protein-coupled receptor signaling pathway; platelet activation; positive regulation of cell adhesion mediated by integrin; positive regulation of chemotaxis; positive regulation of integrin activation by cell surface receptor linked signal transduction; positive regulation of microglial cell migration; positive regulation of phosphatidylinositol 3-kinase/protein kinase B signal transduction; positive regulation of ruffle assembly; regulation of chemotaxis; regulation of microglial cell migration; response to axon injury; substrate-dependent cell migration, cell extension; blood coagulation; G protein-coupled adenosine receptor signaling pathway; G protein-coupled purinergic nucleotide receptor signaling pathway; visual system development
Cellular component: cell surface; membrane; plasma membrane; cell body membrane; cell projection membrane
Genetic constraint (gnomAD): Loss-of-function variants: 5 observed, 9.05 expected, observed/expected ratio (o/e) 0.55, 90% interval 0.29 to 1.16. That is too few expected variants to judge how well the gene tolerates losing a copy. Missense variants: 356 observed, 427.44 expected, observed/expected ratio (o/e) 0.83, 90% interval 0.76 to 0.91. Synonymous variants: 148 observed, 162.36 expected, observed/expected ratio (o/e) 0.91, 90% interval 0.8 to 1.04.
Gene-disease validity (ClinGen):
ClinGen rates the evidence that P2RY12 causes each of these diseases.
platelet-type bleeding disorder 8 (autosomal recessive): Definitive.
platelet-type bleeding disorder 8 (autosomal dominant): Moderate.
Homologues: Orthologues: macaque P2RY12 (98% identical), dog P2RY12 (93% identical), pig P2RY12 (92% identical), mouse P2ry12 (87% identical), rat P2ry12 (86% identical), tropical clawed frog p2ry12 (63% identical), zebrafish p2ry12 (53% identical). Paralogues in human: P2RY13 (44% identical), P2RY14 (44% identical), GPR87 (39% identical), GPR171 (30% identical), GPR34 (26% identical), PTAFR (26% identical).
Diseases named in the same sentence as P2RY12 in open-access papers:
P2RY12 is named in the same sentence as 205 diseases in open-access papers, as found by Europe PMC text mining. Sharing a sentence is not in itself a finding about the gene and the disease. The quoted sentences say what the papers report.
acute coronary syndrome (149 papers, 2010 to 2026). Signs and symptoms related to acute ischemia of the myocardium secondary to coronary artery disease. "Moreover, the pharmacological effects of the drug clopidogrel which binds to and inhibits P2RY12 function are affected by this single nucleotide polymorphism in patients with acute coronary syndrome." (PMID 37237520, 2023).
Stroke (118 papers, 2010 to 2026). Sudden impairment of blood flow to a part of the brain due to occlusion or rupture of an artery to the brain. "These stroke-associated white matter microglia (SAWM) showed lower expressions of the homeostatic microglial markers (P2ry12, Tmem119, etc.)along with elevated expressions of the DAM- and/or MGnD-related genes (Apoe, Trem2, Ctsb, Ctsd, etc.)." (PMID 38509618, 2024). "The statistical analysis showed a significant increase in the relative frequency of the CD45high subpopulation as a percent of Tmem119+ cells after stroke which was associated with a significant decrease in Tmem119 and P2RY12 expressions." (PMID 33261619, 2020). "The downregulation of homeostatic genes such as P2RY12 has been described after inflammatory conditions that occur for instance after stroke." (PMID 36629019, 2023). "In the ischemic penumbra, outside of the stroke core, microglia had reduced process ramification, reduced P2RY12 and TMEM119 protein expression, and less frequent or reduced CXCL10 expression." (PMID 32573436, 2020). "Future experiments that include the analyses of the brain tissue, blood, and brain lymphatic samples after a stroke at multiple time points will be of great value in clarifying potential sources of Tmem119+P2RY12+ cells following ischemia." (PMID 33261619, 2020). "Blockade of P2RY12, by genetic deletion in microglia or by pharmacological antagonists reduces neuronal injury in experimental stroke lesions." (PMID 29222823, 2018). "Indeed, infiltrating MDMs can adopt a microglial signature in animal models of multiple sclerosis and a significant proportion of CD45hi cells express bona fide microglial markers like Tmem119 and P2ry12 in models of stroke and cerebrovascular degeneration." (PMID 37248507, 2023). "Therefore, it is essential to further characterize the potential links between post-stroke treatment with P2RY12 inhibitors and cognitive decline due to their inhibition of microglial P2RY12." (PMID 37511466, 2023). "P2RY12 is considered a homeostatic microglia marker because of its downregulation in neurogenerative and neuroinflammatory models, including amyotrophic lateral sclerosis, AD and MS, which have been more extensively investigated than encephalitis and stroke." (PMID 34853891, 2022). "Considering P2RY12 is upregulated by microglia in stroke and is required for the control of viral spread in PRV encephalitis, it may not be a general homeostatic microglia marker as currently proposed." (PMID 34853891, 2022). "Clopidogrel is a purinergic receptor P2Y12 (P2RY12)-blocking pro-drug used to inhibit platelet aggregation in patients at risk for major adverse cardiac events (MACE), such as coronary artery disease and stroke." (PMID 35647265, 2022). "Unsupervised analysis of the flow cytometry data with respect to the seven surface parameters of CD45, CD11b, MHC-II, CD80, P2RY12, and Tmem119 detected several subsets of MG, lymphocytes and infiltrating monocytes visualized as a phonographic comparison of the vehicle and treated GF stroke brains." (PMID 37790313, 2023). "For a typical instance, ticlopidine (purinergic receptor P2Y12 inhibitor), which is an anti-coagulant drug to prevent the transient ischemic attack (TIA) and stroke, and has been shown to be effective for low-grade glioma and high-grade astrocytoma." (PMID 31164151, 2019). "Similarly, in two stroke models, macrophages infiltrating the CNS or ectopically placed in peri-infarct areas, became TMEM119+ and/or P2RY12+ and/or Sall1+." (PMID 34311763, 2021).
diabetes (65 papers, 2008 to 2026). "Expression of P2ry12, the gene that encodes the P2Y12 purinergic receptor, was more depressed by diabetes in retinal compared to cortical microglia, a change paralleled by reduced expression of a second purinergic receptor gene, P2ry6, in retinal microglia." (PMID 40940761, 2025).
COVID-19 (31 papers, 2021 to 2025). A disease caused by infection with severe acute respiratory syndrome coronavirus 2. "The proximity score of promethazine was significantly low partly by targeting genes including CALM1, KCNS1, LPAR4, LPAR6, P2RY12, P2PY8, and P2RX5, which were DEGs between T cell subsets of COVID-19 samples and healthy controls." (PMID 33919660, 2021).
ischemic stroke (29 papers, 2015 to 2026). A stroke disorder caused by obstruction of blood flow to the brain, due to thrombotic (local blood clot formation) or embolic (due to a blood clot or other material traveling from another site) event. "Among the downregulated genes, Gpr88, Rgs9, Enthd1, Olr59, P2ry12, Degs2, Pde10a, Neu2, Adora2a, and Slc22a6 were found to demonstrate significant downregulation in pathological phase of ischemic stroke." (PMID 25861363, 2015). "Finally, we show that P2ry12-CreER can be used to label microglia in middle cerebral artery occlusion (MCAO)-induced ischemic stroke, as well as experimental autoimmune encephalomyelitis (EAE), a model of multiple sclerosis." (PMID 32573436, 2020). "To explore the detailed transcriptional changes of the highly heterogenous microglia after ischemic stroke, we reclassified microglia and found seven distinct microglia subclusters, MG0–MG6, which all expressed canonical microglia genes, including P2ry12, Hexb, Sparc, and Olfml3." (PMID 37183260, 2023).
Sepsis (28 papers, 2017 to 2026). Sepsis is defined as life-threatening organ dysfunction caused by a dysregulated host response to infection. "The inflammatory damage that the platelet suffers during sepsis activates the purinergic receptor P2Y12 through ADP, which is present in platelets and T lymphocytes and, for this reason, blocking P2Y12 improves the sepsis outcome." (PMID 34946826, 2021). "Our data suggest for the first time that the purinergic receptor P2Y12 and P2Y1 influence sepsis-induced activity of MPO in lungs and kidneys, circulating cytokines, platelet activation and platelet-leukocyte interaction differently in male and female mice." (PMID 36405709, 2022). "However, it has been shown that P2RY12 is lost in a major subpopulation of microglia in the normal human brain and it was a surprise that systemic immune activation in sepsis did not lead to a further downregulation of its expression in microglia." (PMID 29804289, 2019).
glioma (23 papers, 2017 to 2025). A benign or malignant brain and spinal cord tumor that arises from glial cells (astrocytes, oligodendrocytes, ependymal cells). "Previous studies have suggested that the cytoplasmic expression of P2RY12 is associated with the expression of M1 markers and low-grade glioma, while the nuclear expression of P2RY12 is associated with the expression of M2 markers and high-grade glioma." (PMID 33408717, 2020). "(a) The log-fold change expression of SGmic genes (P2ry13, P2ry12, Gpr34, Slc2a5, Siglec-H, Olfml3, Tmem119, Fcrls) in glioma-associated microglia isolated from experimental RCAS tumors compared to microglia isolated from healthy control brains is shown." (PMID 30764877, 2019). "(c) Graph shows the log-fold change expression of SGmic genes (P2ry13, P2ry12, Gpr34, Slc2a5, Siglec-H, Olfml3, Tmem119, Fcrls) in glioma-associated microglia isolated from GL261 tumors as compared to microglia isolated from healthy control brains." (PMID 30764877, 2019). "(b) The log-fold change expression of SGmic genes (P2ry13, P2ry12, Gpr34, Slc2a5, Siglec-H, Olfml3, Tmem119, Fcrls) in glioma-associated microglia isolated from RCAS tumors compared to microglia isolated from healthy control brains is shown." (PMID 30764877, 2019). "Furthermore, a TCGA-based analysis demonstrated that higher levels of P2ry12 expression correlated with a decreased risk of glioma recurrence." (PMID 39409905, 2024). "Unsurprisingly, the increased expression of P2ry12 in glioma is associated with increased survival, whereas a reduction in cytoplastic P2ry12 signal may correlate with a more severe glioma grade." (PMID 39409905, 2024). "We have demonstrated that microglia can be delineated from TAMs in immunohistochemically stained human glioma tissue using the immunoreactivity of microglial-specific markers P2RY12 and TMEM119." (PMID 34286275, 2021). "The results revealed that the expression of CD163 and FPR3 were increasing in glioma, especially in GBM, the expression of P2RY12 was high in glioma, but more notable in LGG." (PMID 33408717, 2020). "P2RY12 mRNA levels and membrane-bound localization of P2RY12 were inversely correlated with increasing malignancy grade, and the expression site of P2RY12 shifted from cytoplasmic in low-grade gliomas, to nuclear in high-grade tumors." (PMID 28073370, 2017). "We conclude that P2RY12 is a specific marker for resident microglia in glioma and its expression and localization correspond to tumor grade and predominant stage of M1/M2 immune response." (PMID 28073370, 2017). "In the GEO dataset GSE 86573 generated from a murine glioma model the expression of P2ry12 by microglia (MG) was significantly higher than that by bone marrow- derived macrophages (BMDM)." (PMID 28073370, 2017). "P2RY12 serves as a prototypical example of altered microglial markers during brain disorders, and a decrease in its expression is a prominent feature of microglia in Alzheimer’s disease and glioma." (PMID 37365324, 2023). "Interestingly, low-grade gliomas expressed P2RY12 in cytoplasm, while, in high-grade tumors, P2RY12 expression shifted to the nucleus." (PMID 33561958, 2021). "P2RY12 is also relevant to M1 and M2 macrophages according to its location in cells nuclear or cytoplasmic and also differentially expressed between microglia and peripheral monocytes/macrophages in health and glioma." (PMID 33408717, 2020). "The pattern of TAM development in glioma started first with a microglia phenotype (P2RY12+/TMEM119+), then it turned to polarized macrophage (CD163+), and finally converged into M2b macrophages (IL1RN+) with activated expression of strong angiogenesis signaling molecules (VEGFA)." (PMID 34692159, 2020). "In this study, we scrutinized P2RY12 as a marker for microglial cells in glial tumors." (PMID 28073370, 2017).
glioma (continued). "Here we analyzed the expression of P2RY12 in astrocytomas of various malignancy grades in relation to markers for M1 and M2 macrophage activation profiles by using two web-based glioma datasets and confocal immunohistochemistry to 28 astrocytoma samples grades II-IV." (PMID 28073370, 2017). "More recently, P2RY12 and CD49d were proposed to be robust markers for TAM-MGs and TAM-MDMs, respectively, after lineage-tracing studies were conducted in mice and validation studies were conducted with human glioma specimens." (PMID 37365324, 2023). "Some researches had studied CD163, P2RY12 and PLAUR as biomarkers in glioma." (PMID 33408717, 2020). "In the gliomas, P2RY12 immunoreactivity delineated CD68 negative cells with otherwise microglial features from CD68 positive tumor associated macrophages (TAMs)." (PMID 28073370, 2017). "Likewise, IRF8, a transcription factor for the function and development of microglia cells is expressed simultaneous with P2RY12 in both GBM and low grade gliomas." (PMID 28073370, 2017). "Bioinformatic analyses of scRNA seq datasets of eighteen glioma patients (two with low-grade glioma, eleven with newly diagnosed glioblastoma, and five with recurrent glioblastoma) demonstrate that SIRPA is expressed in myeloid cells, and multiplex imaging shows P2RY12+ microglia also express SIRPα." (PMID 38786045, 2024).
multiple sclerosis (22 papers, 2013 to 2025). A progressive autoimmune disorder affecting the central nervous system resulting in demyelination. "For example, the expression of P2ry12 in microglia is decreased in Alzheimer’s disease and multiple sclerosis and increased in ischemic stroke." (PMID 37047745, 2023). "Similarly, other reports also found activated microglia with high P2RY12 expression in pre-active and chronic white matter lesions of multiple sclerosis and in diffuse β-amyloid plaques in human samples." (PMID 33328887, 2020). "Our results showing decreased expression levels of P2ry12 during IRI are in line with previous studies investigating CNS disorders such as Alzheimer’s disease, multiple sclerosis, and amyotrophic lateral sclerosis." (PMID 37047745, 2023). "Previous reports have shown that microglia located near multiple sclerosis (MS) lesions or amyloid plaques in human brains lose expression of P2RY12, a phenomenon not observed in schizophrenia patients." (PMID 39828750, 2025).
ischemia (19 papers, 2013 to 2026). A hypoperfusion of the BLOOD through an organ or tissue caused by a PATHOLOGIC CONSTRICTION or obstruction of its BLOOD VESSELS, or an absence of BLOOD CIRCULATION. "In a rodent ischemia model, blockade of microglial P2RY12 with ticagrelor, an antagonist, reduced ischemic damage by microglia by reducing their migration to sites of injury." (PMID 31968618, 2020). "Remarkably, ischemia-associated microglia (amoeboid-like CXCL10+ cells lacking P2RY12 and TMEM119 protein expression) filled the lesion core." (PMID 32573436, 2020). "In another ischemia animal model, and with an in vitro model of oxygen–glucose deprivation (OGD), inhibition of microglia P2YR12 with clopidogrel, another antagonist, or by P2RY12 gene expression knock-down significantly reduced microglial migration and neurotoxicity." (PMID 31968618, 2020).
Alzheimer disease (14 papers, 2018 to 2024). A progressive, neurodegenerative disease characterized by loss of function and death of nerve cells in several areas of the brain leading to loss of cognitive function such as memory and language. "We have shown previously that the loss of P2RY12 reactivity correlates with the extent of neurodegeneration in human cortex of controls and Alzheimer's disease patients." (PMID 29804289, 2019). "There was also reduced microglial expression of CX3CR1 and P2RY12 as they adopted a disease-associated phenotype in mouse models of Alzheimer’s disease and MS." (PMID 30087595, 2018). "Dysfunctional microglia in the post-mortem Alzheimer’s disease brain are characterised by the downregulation of homeostatic markers, including P2RY12 and TMEM119, and the up-regulation of dysfunctional markers, including L-ferritin." (PMID 37118836, 2023). "Consistent with recent studies in pre-clinical models of Alzheimer’s disease (AD) and EAE, we also report both Tmem119 and P2RY12 expression are decreased after acute ischemic stroke, after the development of symptoms in CAA models, and in ex vivo models of inflammation for sorted MG." (PMID 33261619, 2020).
atherosclerosis (14 papers, 2014 to 2025). A disease characterized by the build-up of fatty material and calcium deposition in the arterial wall resulting in partial or complete occlusion of the arterial lumen. "Genes such as COMP (cartilage oligomeric matrix protein), CHI3L1, PLA2G2A, P2RY12, CR1, HPSE (heparanase), PTX3 and SERPINE1 were related to atherosclerosis." (PMID 34218797, 2021).